MTOR (mechanistic target of rapamycin kinase)
Diseases named in the same sentence as MTOR in open-access papers (continued):
Sharing a sentence is not in itself a finding about the gene and the disease.
cancer (continued). "Therefore, therapeutic targeting of the PI3K/Akt/mTOR axis by means of small molecule inhibitors is being pursued as an option for innovative treatment of several types of cancers." (PMID 24281174, 2010). "Rapamycin analogues, such as temsirolimus (CCI-779) or everolimus (RAD-001) that target mTOR are now in different stages of clinical trials for anti-cancer therapy as a single agent or as additive treatment having synergetic effect with ER- and HER2/neu- targeted therapy." (PMID 19680458, 2010). "Therefore, it is likely that the degree of mTOR inhibition obtained with the current agents in human cancers, including RCC, is insufficient." (PMID 20823888, 2010). "We then highlight how targeting PI3K/Akt/mTOR signaling with small molecules could improve cancer patient outcome." (PMID 24281174, 2010). "Deregulation of the mTOR signaling pathway is reported in many malignancies, and some of the signaling molecules in this pathway are predictors of prognosis in different types of cancers." (PMID 20338061, 2010). "The lack of suitable tumor samples from well annotated clinical trials and the resulting reliance on mouse xenograft and in vitro cancer models has precluded the identification of clinically relevant predictive biomarkers for mTOR inhibitors and anti-angiogenic drugs in RCC and other solid tumors." (PMID 20701793, 2010). "InsP5 and 2-O-Bn-InsP5 may represent lead compounds to develop novel inhibitors of the PI3K/Akt pathway (including potential dual PDK1/mTOR inhibitors) and novel potential anti-cancer drugs." (PMID 20051961, 2010). "The mammalian target of rapamycin (mTOR) pathway is a crucial regulator of cell growth and proliferation and research into this area has revealed that mTOR dysregulation has a key role to play in various cancers." (PMID 21584218, 2010). "Thus far, clinical studies have supported preclinical findings regarding the importance of mTOR in cancer and validate mTOR inhibition as an effective cancer therapy." (PMID 21584218, 2010). "Interestingly, since mTOR inhibitors have both immunosuppressive and anti-cancer effects, they have the potential to simultaneously protect against immunologic graft loss and tumour development." (PMID 20459775, 2010). "As tumor cells frequently acquire defects in autophagy compared with normal cells, pharmacological activation of autophagy through inhibition of Akt/mTOR pathway may kill cancer cells and limit tumorigenesis, especially in cancers with defects in apoptosis." (PMID 20808909, 2010). "Previous studies in various settings have shown that glucose deprivation causes metabolic stress and induces adaptive responses —so-called “starvation response” – manifest by AMPK activation, mTOR inhibition and multiple other biochemical and metabolic changes in cancer cells." (PMID 20844768, 2010). "However, the PI3K/Akt/mTOR signaling pathway represents one of the major survival pathways that is deregulated in many human cancers and contributes to both cancer pathogenesis and therapy resistance." (PMID 20671809, 2010). "Moreover, there is evidence that mTOR activation can lead to anchorage-independent growth of carcinoma cells, making it a potentially important factor for cell survival in effusions." (PMID 19680458, 2010). "While activating mutations in mTOR itself have not been documented in cancer cells, modifications of upstream components that regulate mTOR and downstream effectors of the mTOR pathway have been observed." (PMID 19816606, 2009). "Furthermore, FDG-PET has been used to distinguish between tumours, which are sensitive or resistant to mTOR inhibitors in various preclinical cancer models." (PMID 19436299, 2009).
cancer (continued). "The mammalian target of rapamycin (mTOR), a Ser/Thr protein kinase that mediates intracellular signalling related to cell growth, proliferation, and differentiation, has received considerable interest as a possible target for cancer treatment." (PMID 19223902, 2009). "Dysregulation of mTOR signaling contributes to the pathobiology of human cancer." (PMID 19816606, 2009). "Recent data suggest that combining mTOR with VEGF receptor inhibitors may have clinical potential to enhance survival of cancer patients." (PMID 19473483, 2009). "These discrepancies may be partly explained by differences in the type of cancer studied, in the system used to classify p-Akt staining, or in the expression of downstream targets of p-AKt, such as mTOR." (PMID 19223902, 2009). "Clinical results show that mTOR inhibitors are well tolerated and may induce prolonged stable disease and tumour regression in cancer patients." (PMID 19128503, 2009). "Furthermore, data on the effects of mTOR inhibition on gene expression in cancer cells are extremely limited." (PMID 19816606, 2009). "However, few studies have assessed correlations of mTOR expression in human cancers with either clinocopathological features or outcomes." (PMID 19223902, 2009). "Because mTOR is activated through cellular pathways that are dysregulated in many different types of cancer, single-agent use of mTOR inhibitors could potentially result in anticancer activity in numerous tumor types." (PMID 19860903, 2009). "The concept of searching for cancer drugs through synthetic lethality seems to be more rewarding when either the assay (FOXO1a in PTEN−/−) or the potential target gene (mTOR in PTEN−/−) can be decided upon based on data mining and prior knowledge of the normal and tumourigenic biological system." (PMID 19319136, 2009). "Various cancer and non-cancer human diseases were identified as being significantly associated with the mTOR pathway interactome." (PMID 18980674, 2008). "In contrast in KRAS mutant cancers, a concurrent LKB1 mutation may be required to enhance mTOR activation." (PMID 18594528, 2008). "Our results provide the first clinical evidence that caveolin-1 cooperates with an activated AKT/mTOR pathway in cancer and may play an important role in disease progression." (PMID 18283322, 2008). "In the present study, we demonstrated that blocking mTOR activity might induce inhibition of cancer cell proliferation and survival." (PMID 18319715, 2008). "The mammalian target of rapamycin (mTOR) has emerged as an important therapeutic target for cancer." (PMID 19384426, 2007). "PKB/Akt and mTOR thus present important therapeutic targets for anti-cancer agents." (PMID 17407548, 2007). "The role of mTOR in cell growth, metabolism, and cancer has been reviewed extensively." (PMID 16953237, 2006). "The regulation of TSC2 and mTOR by AMPK might have special implications because the PI3K-Akt signalling pathway is constitutively active in many cancers." (PMID 16570048, 2006). "Thus, the 4E-BPs are considered to be important mTOR targets that modulate cancer cell growth through a mechanism that involves cap-dependent translation." (PMID 16404421, 2006). "The immunosuppressant rapamycin specifically inhibits mTOR activity and retards cancer growth." (PMID 16404421, 2006). "Notably, integration of the BLV genome has been identified near the genes that play a role in cancer development, such as in the intergenic region of RTN4IPI and ATG5, and in the intron of the regulatory-associated protein of mTOR (RPTOR) in two B-cell lymphoma lines." (PMID 41596377, 2026). "The PI3K/AKT/mTOR signaling pathway may also affect cancer cells and host immunity." (PMID 40717210, 2025). "Therefore, we believe that ongoing in vitro studies focusing on blocking the PI3K/AKT/mTOR /NF-kB pathways would be interesting and provide promising results that may enhance the efficiency of anti-cancer therapeutics." (PMID 41180483, 2025).
cancer (continued). "Broader studies have shown that ASNS’s impact on cancer progression and therapy response is tightly interwoven with other metabolic vulnerabilities, including glutamine, arginine, and polyamine dependency, and the tightly regulated crosstalk between mTOR, NOTCH, and GCN2 signaling pathways." (PMID 41463097, 2025). "mTOR protein can drive tumor growth and progression through various mechanisms, such as enhancing growth factor receptor signaling, promoting angiogenesis, supporting glycolytic and lipid metabolism, facilitating cancer cell migration (metastasis), and inhibiting autophagy." (PMID 40287470, 2025). "Furthermore, the exact mechanisms by which miR-99a controls the PI3K/AKT/mTOR pathway in various cancers are yet unknown, which makes further molecular investigations necessary." (PMID 40167762, 2025). "Since PI3K/Akt/mTOR signaling dysregulation plays a crucial role in cancer drug resistance, discovering new compounds targeting these components could help overcome drug resistance in various cancer therapies." (PMID 40179064, 2025). "Targeting mTOR signaling as a regulatory mechanism that promotes fatty acid uptake and synthesis may offer a strategic approach to overcoming potential resistance mechanisms in cancer treatment." (PMID 40641601, 2025). "Additionally, silver nanoparticles inhibit tumor growth by interfering with key signaling pathways like PI3K/Akt/mTOR and reduce metastasis by inhibiting cancer cell migration and invasion, often through disruption of the extracellular matrix and interaction with matrix metalloproteinases (MMPs)." (PMID 40248096, 2025). "Additionally, many radioresistant cancers exhibit an active PI3K/Akt/mTOR signaling pathway." (PMID 40895189, 2025). "The upregulation of GOLPH3 might also influence mTOR signaling through its effects on glycosylation, which influences the endocytosis and recycling of cancer-relevant glycoproteins that act upstream of the mTOR complex, leading to prolonged growth factor signaling." (PMID 40136688, 2025). "In this context, a recent paper investigated the role of mLST8 in a panel of normal and cancer cells showing that mLST8 loss, or even a single pair of mutations affecting mTOR binding, completely impaired mTOR association with mTORC2 cofactors RICTOR and SIN1 without affecting mTORC1." (PMID 40136688, 2025). "Furthermore, monitoring mTOR activity is critical in cancer care." (PMID 40717210, 2025). "Thus, we conclude that FFX potentiates MYC and augments mTOR signaling in human cancer." (PMID 40027648, 2025). "Other evidence indicates that mTOR activation may have a favorable role in cancer patients." (PMID 40944200, 2025). "Lung cancer-derived TGFβ activates the Smad2/3 and Akt/mTOR pathways in pericytes, inducing their transition into myofibroblasts that excessively produce ECM proteins such as collagen and fibronectin, in turn ultimately causing structural alterations in blood vessels and cancer cell invasion." (PMID 41429896, 2025). "In addition, catechins may inhibit the PI3K/Akt/mTOR pathway, which is frequently dysregulated in cancer." (PMID 41614832, 2025). "Besides, SCD1 expression is modulated by mTOR signaling pathway in cancer cells." (PMID 40053468, 2025). "Furthermore, the interaction between miRNAs and PI3K inhibitors could regulate key oncogenic pathways in the PI3K/AKT/mTOR pathway and improve targeted cancer therapies." (PMID 40142329, 2025). "Therefore, mTOR inhibitors are key candidates for human cancer therapy." (PMID 40563640, 2025). "While YAP/TAZ signaling has more recently emerged as one of the signaling pathways implicated in both cancer and NDDs, the most prominent examples where molecular mechanisms that promote cancer development/progression and NDDs intersect are the Ras/MAPK pathway and PI3K/mTOR signaling." (PMID 39936032, 2025).
cancer (continued). "Therefore, the effect of 1 might not be dependent on AR, 1 might suppress proliferation and metastasis in PCa by disrupting other key cancer signaling pathways like mTOR/AKT and STAT3." (PMID 40374533, 2025). "Evidence strongly proposes that MYC/mTOR-driven tumorigenic signaling can predominantly control the translational machinery to elicit cooperative effects on increased cell proliferation, cell cycle progression, and genome dysregulation as a mechanism of cancer initiation." (PMID 39779613, 2025). "Moreover, inhibition of the PI3K/Akt/mTOR signalling pathway by Ly294002 could reverse the expression of the key enzymes of the Warburg effect, stem cell reprogramming factors and cancer cell stemness markers which were promoted by the overexpression of HBx." (PMID 40717222, 2025). "Furthermore, the activation of AKT/mTOR signaling by NRG1 induces high expression of PDGFC in cancer cells, which in turn promotes the activation of fibroblasts and NRG1 expression through the release of PDGFC, forming a positive feedback loop between NRG1 and PDGFC." (PMID 41213930, 2025). "Finally, targeting mTOR pathways using plant‐derived chemicals may be a promising therapy strategy for cancer." (PMID 40717210, 2025). "Therefore, one strategy to block the mTOR complex and reduce its proliferative function in cancer may be to activate Gαs‐coupled GPCRs." (PMID 40969301, 2025). "Because mTOR plays an important role in nutrient sensing and cell metabolism, it may act as a regulator of energy homeostasis, particularly metabolic regulation in cancer cells." (PMID 41013205, 2025). "For example, the predicted sensitivity to mTOR inhibitors in the high-risk group contrasts with some preclinical evidence suggesting that KRAS-driven cancers, potentially relevant to pathways enriched in our high-risk group, might exhibit resistance to PI3K/mTOR pathway inhibition." (PMID 40607411, 2025). "Additionally, PA is a key regulator of mTOR signaling, a pathway frequently activated in EC, which may contribute to altered lipid metabolism and cancer progression." (PMID 40710558, 2025). "However, data from the BC mouse model suggest that mTOR inhibition might induce a stem cell phenotype in cancer cells, and in the experimental metastasis model, increase the number of lung metastases." (PMID 41046340, 2025). "The PI3K/AKT/mTOR pathway plays an important role in various processes of irradiated tumor cells, including DNA repair, cell cycle regulation, proliferation, apoptosis, autophagy, hypoxia, cancer stem cell self-renewal, invasion, and metastasis, as described in the next chapters in more detail." (PMID 40725100, 2025). "Therefore, alternative strategies focusing on mTOR‐independent autophagy activation might offer significant benefits for cancers displaying drug resistance." (PMID 40014262, 2025). "Consequently, mTOR has emerged as a significant target for anti-cancer targeted therapy." (PMID 39948481, 2025). "Thus, using NVP-BEZ235 to inhibit PI3K/AKT/mTOR signaling may result in cell cycle arrest in cancer cells." (PMID 40771929, 2025). "We present a reproducible, pan-cancer, network-aware framework that integrates curated resources with genomics to move beyond pathway curation, yielding falsifiable hypotheses and prioritized candidates for mTOR axis biomarker validation." (PMID 41300706, 2025). "Thus, both AMPK and mTOR play significant roles in the regulation of autophagy in human cancers." (PMID 39403142, 2024). "Therefore, inhibiting autophagy with mTOR inhibitors at specific times may increase the metabolic stress on cancer cells to facilitate cell death." (PMID 38755125, 2024).
cancer (continued). "In addition, the Wnt/β-catenin and Akt/mTOR signaling pathways support the survival of cancer stem-like cells (CSCs), which may contribute to drug resistance." (PMID 38891932, 2024). "Consequently, mTOR hyperactivation is frequently found in human cancers." (PMID 38272224, 2024). "Understanding how mTOR signaling utilized by cancer cell allows them to survive the challenges they face during tumor progression due to anoikis, nutrient deprivation, and other forms of stress could highlight previously unappreciated vulnerabilities and open the way toward designing new therapies." (PMID 36711811, 2024). "Evidence suggests that the PI3K/Akt/mTOR and Hippo pathways are pivotal in conferring resistance of cancer cells to chemotherapy; hence, modulation of these pathways could represent a promising approach for cancer therapy." (PMID 39702299, 2024). "There is also evidence that well-characterised lncRNAs such as MALAT1 and urothelial carcinoma-associated 1 (UCA1) regulate processes upstream of mTOR and that this indirect regulation of mTOR could largely be behind the involvement of these lncRNAs in cancer processes." (PMID 39062685, 2024). "However, some bioactive compounds can accelerate cancer by activating mTOR signaling." (PMID 39723045, 2024). "Additionally, mTOR inhibitors could improve cancer-free survival after transplantation and have a nephroprotective potential." (PMID 38341510, 2024). "Therefore, therapies aimed at enhancing MLIP expression or its regulatory effect on the PI3K/Akt/mTOR pathway might be beneficial for inhibiting cancer progression." (PMID 38994962, 2024). "Thus, the hypothesis suggests a synergistic action in which SsnB increases ceramide levels, which either directly or indirectly inhibits the PI3K/AKT/mTOR pathway, leading to enhanced apoptosis and reduced cancer cell viability." (PMID 39770406, 2024). "Because the synergistic effect of chemo-immunotherapy has generated much interest as a new therapeutic strategy, mTOR signaling may be a potential therapeutic target for cancer therapy as a central regulator for tumor progression and immune evasion in tumor-bearing hosts." (PMID 38791040, 2024). "Interestingly, further GSEA analysis showed that the "PI3K-Akt signaling pathway", "T cell receptor signaling pathway", "mTOR signaling pathway" and "PD-L1 expression and PD-1 checkpoint pathway in cancer" were significantly activated in PLCG2 high-expression group." (PMID 39494327, 2024). "Many common diseases exhibit uncontrolled mTOR signaling, prompting considerable interest in the therapeutic potential of mTOR inhibitors, such as rapamycin, to treat a range of conditions, including cancer, aging-related pathologies, and neurological disorders." (PMID 39107687, 2024). "Therefore, drugs/agents targeting mTOR have been developed for cancer treatment." (PMID 38255807, 2024). "Others have demonstrated the use of sapanisertib in clinical trials in conjugation with metformin, a widely used drug for treating T2D that also exhibits mTOR inhibitory functions, which could further enhance the antitumor effects, preventing cancer progression." (PMID 39770519, 2024). "Furthermore, mTOR has been shown to regulate miRNAs − 101-3p in several cancer cells." (PMID 38965615, 2024). "Moreover, the mTOR signaling pathway may be involved in immune evasion in cancer via driving immunosuppressive features." (PMID 38791040, 2024). "Importantly, we uncover the critical role of mTOR signaling in regulating the phagocytic capacity of macrophages toward cancer cells via controlling phagosome maturation and mediating the transition between non-phagocytic and phagocytic states of macrophages in the presence of cancer cells." (PMID 39766137, 2024). "Thus, we hypothesized that combining PegC with mTOR inhibition would enhance the anti-cancer effect in PDAC models." (PMID 38951899, 2024).